DUSP6 (dual specificity phosphatase 6)
Description:
Dual specificity protein phosphatase, which mediates dephosphorylation and inactivation of MAP kinases. Has a specificity for the ERK family. Plays an important role in alleviating chronic postoperative pain (By similarity). Necessary for the normal dephosphorylation of the long-lasting phosphorylated forms of spinal MAPK1/3 and MAP kinase p38 induced by peripheral surgery, which drives the resolution of acute postoperative allodynia (By similarity). Also important for dephosphorylation of MAPK1/3 in local wound tissue, which further contributes to resolution of acute pain (By similarity). Promotes cell differentiation by regulating MAPK1/MAPK3 activity and regulating the expression of AP1 transcription factors.
Synonyms: MKP-3; MKP3; PYST1; HH19
Tractability: PROTAC: UniProt records ubiquitination sites on it; ubiquitination databases record sites on it; a small molecule that binds it is known.
Target class: Phosphatase; Serine/threonine/tyrosine protein phosphatase; Enzyme; Protein Phosphatase
Gene: Protein-coding gene on chromosome 12 (89,347,235 to 89,352,501, reverse strand). Ensembl gene ENSG00000139318.
Subcellular location: Cytoplasm
Subcellular location (Human Protein Atlas): Cytosol; Nucleoplasm
Pathways (Reactome):
Signal Transduction: ERKs are inactivated; Negative regulation of MAPK pathway; RAF-independent MAPK1/3 activation
Disease: Signaling by MAPK mutants
Gene Ontology:
Molecular function: MAP kinase tyrosine/serine/threonine phosphatase activity; protein binding; protein serine/threonine phosphatase activity; protein tyrosine phosphatase activity; MAP kinase tyrosine phosphatase activity; protein tyrosine/serine/threonine phosphatase activity; protein tyrosine/threonine phosphatase activity; phosphoprotein phosphatase activity
Biological process: negative regulation of ERK1 and ERK2 cascade; negative regulation of MAPK cascade; peptidyl-tyrosine dephosphorylation; positive regulation of apoptotic process; response to nitrosative stress; ERK1 and ERK2 cascade; MAPK cascade; regulation of heart growth; cell differentiation; response to growth factor; response to xenobiotic stimulus
Cellular component: cytoplasm; cytosol; nucleoplasm
Genetic constraint (gnomAD): Loss-of-function variants: 6 observed, 26.31 expected, observed/expected ratio (o/e) 0.23, 90% interval 0.12 to 0.45. The upper end of that interval is the gene's LOEUF score, 0.45, which puts it in group 1 of 6, group 1 being the genes least tolerant of losing a copy. Missense variants: 451 observed, 514.8 expected, observed/expected ratio (o/e) 0.88, 90% interval 0.81 to 0.95. Synonymous variants: 252 observed, 222.6 expected, observed/expected ratio (o/e) 1.13, 90% interval 1.02 to 1.26.
Homologues: Orthologues: chimpanzee DUSP6 (99% identical), dog DUSP6 (99% identical), macaque DUSP6 (99% identical), pig DUSP6 (99% identical), rabbit DUSP6 (99% identical), guinea pig DUSP6 (99% identical), rat Dusp6 (99% identical), mouse Dusp6 (98% identical), tropical clawed frog dusp6 (88% identical), zebrafish dusp6 (81% identical). Paralogues in human: DUSP7 (71% identical), DUSP9 (55% identical), DUSP16 (30% identical), DUSP1 (29% identical), DUSP2 (29% identical), DUSP8 (28% identical), DUSP4 (28% identical), DUSP10 (28% identical), SSH1 (27% identical), DUSP5 (27% identical), SSH2 (25% identical), SSH3 (23% identical), and 19 more.
Diseases named in the same sentence as DUSP6 in open-access papers:
DUSP6 is named in the same sentence as 156 diseases in open-access papers, as found by Europe PMC text mining. Sharing a sentence is not in itself a finding about the gene and the disease. The quoted sentences say what the papers report.
melanoma (36 papers, 2005 to 2025). A malignant, usually aggressive tumor composed of atypical, neoplastic melanocytes. "The rapid loss of DUSP6 expression correlated with an increase in p-ERK levels in both melanoma genetic subtypes." (PMID 39436655, 2024). "BRAFV600E, or RAS with BRAF and NRAS mutated cell lines, showed higher levels of DUSP6 expression, compared to melanoma cell lines carrying wild type BRAF and NRAS." (PMID 31416288, 2019). "As expected for a tumor suppressor, the knockdown either promoted cell growth or did not exert any effect, while the same knockdown in BRAF V600E melanoma with high DUSP6 expression caused cell death via induction of apoptosis." (PMID 28423600, 2017). "However, specifically in the context of mutant Braf–driven melanoma they found that siRNA-mediated knockdown of DUSP6/MKP-3 caused apoptosis." (PMID 30401534, 2019). "Our hypothesis led to the identification of DUSP6 as a potential synthetic lethal target in melanoma with BRAF V600E mutation and high expression of DUSP6, suggesting that, in certain scenarios, this tumor suppressor may serve as drug target." (PMID 28423600, 2017). "A main finding of additional proof-of-concept experiments was that the tumor suppressor DUSP6 could serve as a potential synthetic lethal drug target in melanoma with BRAF V600E mutations." (PMID 28423600, 2017). "Moreover, its previously established role in the negative control of ERK signaling in BRAFV600E as well as NRAS-mutant melanoma cells suggested that DUSP6 loss could drive the observed ERK hyperactivation." (PMID 39436655, 2024). "On the other hand, Lee and colleagues have reported that the increased expression of Mir-211 impairs the antitumoural role of DUSP6 in melanoma, pointing to the use of non-coding RNAs as an additional strategy to modulate the activity of DUSPs." (PMID 40943262, 2025). "The same effects were observed using A375 and WM902 xenografts in mice, further confirming the protective role of DUSP6 in melanoma." (PMID 40943262, 2025). "In a later work based on IHC of melanoma specimens, it was found that DUSP6 protein, as well as STAG2 and STAG3, two cohesin complex components, are decreased following treatment with BRAF or MEK (dabrafenib, trametinib, andvemurafenib) inhibitors." (PMID 40943262, 2025). "As for melanoma, DUSP6 overexpression in human melanoma cells (A375) reduced tumour xenograft growth in mice." (PMID 40943262, 2025). "BRAF-mutant melanoma cells show higher levels of DUSP6, and its reduction after treatment with BRAFi suggests that loss of negative feedback control over ERK contributes to resistance." (PMID 40872623, 2025). "The loss of these proteins reduces the response of melanoma cells to MAPK pathway inhibition and results in the reactivation of ERK signaling through reduced activity of the DUSP6 phosphatase, responsible for ERK regulation." (PMID 40872623, 2025). "Such instability indicated the presence of a molecular mechanism responsible for rapid, active DUSP6/MKP3 degradation in melanoma cells." (PMID 39436655, 2024). "Our RNA-seq analyses showed significant upregulation of not only EGR1 but also DUSP5 and DUSP6 expression in response to eIF4Fi in both melanoma genetic contexts." (PMID 39436655, 2024). "Another independent confirmation of eIF4F-dependent regulation of DUSP6 levels in melanoma cells was provided by transient transfection of siRNAs specific for the eIF4A1, eIF4G1, and eIF4E transcripts." (PMID 39436655, 2024). "Collectively, the data indicated that eIF4F contributes to the control of ERK activity in melanoma cells by maintaining the continuous production of DUSP6 MAP kinase phosphatase." (PMID 39436655, 2024). "The subsequent analyses confirmed that DUSP6/MKP3 was highly unstable in RocA-treated A375 melanoma cells, with a protein half-life of less than 15 min." (PMID 39436655, 2024).
melanoma (continued). "To exclude the possibility of a previously unidentified eIF4F-independent off-target effect of RocA on DUSP6 protein stability, we treated melanoma cells with 4E1RCat, a structurally unrelated compound inhibiting eIF4F by a different mechanism." (PMID 39436655, 2024). "In BRAFV600E melanoma cells, DUSP6/MKP3 proved essential for controlling the oncogenic ERK signaling." (PMID 39436655, 2024). "DUSP6 is an oncogenic factor in melanoma, and DUSP4 can play its part in the survival and growth of melanoma cells by inhibiting the DUSP6 expression." (PMID 36059641, 2022). "In the present study, we developed a prognostic and diagnostic biomarker with 5 selected MRGs (A2M, DUSP6, HLA-B, SERPINE2, and SLC26A2), all of which acted as risk factors in melanoma." (PMID 33324561, 2020). "This activity suggests a clear relationship with MAPK pathway activation and DUSP6 expression in melanoma." (PMID 31416288, 2019). "Compared with BRAFWT and NRASWT melanoma, significantly higher DUSP6 expression was found in melanoma cells with BRAF and NRAS mutations." (PMID 30577494, 2018). "Our datamining shows that melanoma cell lines express the highest level of DUSP6 mRNA among all cancer cell lines, according to the Cancer Cell Line Encyclopedia (CCLE), and second highest among primary cancer tissues in cBioPortal." (PMID 30577494, 2018). "This indicated inactivation of tumor suppressors, specifically DUSP6, as a counter-intuitive, but conceivable, synthetic lethal therapeutic concept in a subset of melanomas." (PMID 28423600, 2017). "However, a recent work performed using the B16-F10 melanoma cell line demonstrated that hinokitiol, a plant-derived metal chelator, induces an increase in DUSP6 along with a DUSP6-dependent decrease of ERK1/2 phosphorylation and of cell proliferation." (PMID 40943262, 2025). "Finally, overexpression of DUSP6 was shown to counteract the protumoural role of Mir-211 in melanoma." (PMID 40943262, 2025). "Importantly, in a different experiment, a cotreatment with MG132 at least partly rescued the eIF4Fi-induced DUSP6/MKP3 depletion in both melanoma subtypes." (PMID 39436655, 2024). "Similarly, metformin activates ERK/MAPK by enhancing B-Raf (V600E) induced DUSP6 degradation, thus promoting melanoma progression." (PMID 35140333, 2022). "These cells simultaneously became more resistant to the BRAF inhibitor vemurafenib and the MEK inhibitor cobimetinib, suggesting that the modulation of the DUSP6/ERK5 signaling pathway by MIR211 is related to the development of BRAF/MEK inhibitor resistant melanoma." (PMID 33628737, 2020). "Therefore, DUSP6 is now used as a predictive biomarker for the clinical efficiency of MAPK inhibitors in melanoma." (PMID 31416288, 2019). "Interestingly, a recent study showed that melanoma cell lines and primary tissues show some of the highest expressions of DUSP6 among all cancer cell lines and primary tissues tested." (PMID 31416288, 2019). "To investigate this, we performed an siRNA-mediated knockdown of DUSP6 in BRAF wild type melanoma." (PMID 28423600, 2017). "The results of a systematic proof-of-concept cell viability screen led to subsequent hypothesis-based experiments, which identified DUSP6 as context-specific synthetic lethal target in melanomas with BRAF V600E mediated ERK1/2 activation." (PMID 28423600, 2017). "We therefore hypothesize that elevated DUSP6 levels in melanoma are one mechanism for compensating BRAF V600E hyperactivation, which might otherwise trigger apoptosis via ERK1/2 downstream targets." (PMID 28423600, 2017).
melanoma (continued). "In the same in vivo model, they also demonstrated that Mir-211 overexpression confers resistance to vemurafenib (BRAFi) and cobimetinib (MEKi) through the activation of ERK5, a MAPK supporting melanoma growth, suggesting that DUSP6 may potentially prevent this undesirable effect." (PMID 40943262, 2025). "Absence of mutation of DUSP5 and DUSP6 reported in thyroid cancers as well as in melanomas support the hypothesis that these phosphatases have no tumor suppressor role in this type of carcinoma." (PMID 28910386, 2017). "Crucially, we observed a rapid downregulation of DUSP6, followed by DUSP5 induction at later time points, in both melanoma genetic subtypes, confirming the observations made with RocA." (PMID 39436655, 2024). "By controlling the production of DUSP6 and maintaining spare signaling capacity, eIF4F contributes to the optimal ERK signaling flux in treatment-naïve melanoma cells." (PMID 39436655, 2024). "Reactivation of ERK signaling is mediated by deregulation of the expression of dual specificity phosphatase 6 (DUSP6), an inhibitor and regulator of ERK activity in melanoma, which is mediated by CCCTC-binding factor (CTCF) and by the loss of STAG2." (PMID 38672652, 2024). "First, we analyzed the impact of CR-1-31-B on DUSP6 levels and the ERK pathway activity in A375 melanoma cells using Western blot." (PMID 39436655, 2024). "We further validated the results from our screen by individually silencing the expression of DUSP4 and two other DUSP family members with roughly similar substrate selectivity (DUSP6 and DUSP10) in two different BRAFV600E melanoma cell lines." (PMID 35580987, 2022). "In this study, we found that treatment of melanoma cells with BCI, a DUSP1/DUSP6 inhibitor at a concentration close to IC50 for selective inhibition of DUSP1, caused upregulation of nestin and immature MAP2 in MAPKi-sensitive cells." (PMID 35999349, 2022). "It has been reported that BOP1 knockdown resulted in the downregulation of the MAPK phosphatases DUSP4 and DUSP6 and further increased MAPK signaling and resistance to BRAF kinase inhibitors in melanoma." (PMID 32167616, 2020). "In our model high expression of DUSP6 and DUSP14 is predictive of resistance to paclitaxel in melanoma and glioma." (PMID 26274927, 2015). "DUSP6 overexpression prevented cisplatin-dependent induction of both ERCC1 and XPF and restored sensitivity to cisplatin, confirming that DUSP6 has an antitumoural role in melanoma." (PMID 40943262, 2025). "One of the key findings of our study is the identification of DUSP6/MKP3 as a downstream effector of eIF4F in the negative feedback regulation of the ERK pathway in melanoma." (PMID 39436655, 2024). "In melanoma cells, ERK rebound upon BRAFV600E inhibition may be due to reduction of the ERK phosphatase DUSP6 and receptor tyrosine kinase blocker Spry2, which sequesters the Grb2:SOS complex, preventing the binding of receptor tyrosine kinase." (PMID 26023796, 2015). "Interestingly, mutation of PTEN (phosphatase and tensin homolog), and expression of DUSP6 and USP6 (ubiquitin specific peptidase 6) are selected only for melanoma samples." (PMID 26274927, 2015). "Consistently, melanoma cell lines (A375, Mel1617, WM902, WM983, and M14) resistant to BRAFi or MEKi showed reduced expression of STAG2 and STAG3, and their KD led to a further decrease of DUSP6 as well as of BRAFi sensitivity, along with an increase in ERK1/2 phosphorylation." (PMID 40943262, 2025). "Specifically, melanoma cells bearing the most common oncogenic mutation BRAFV600E rely, at least partly, on the activity of the dual-specificity phosphatase DUSP6/MKP3, a negative feedback regulator of ERK signaling, to keep the ERK activity within the optimal range." (PMID 39436655, 2024).
melanoma (continued). "They speculate that DUSP6/MKP-3 might be required to prevent BrafV600E hyperactivation from triggering cell death via ERK1/2 downstream substrates and suggest that it might represent a synthetic lethal drug target in this subset of melanoma patients." (PMID 30401534, 2019). "Moreover, DUSP6 level was reduced already after short treatment of melanoma cells with either vemurafenib or trametinib, which further supports the notion that DUSP6 suppression might not be essential for the development of resistance to targeted therapeutic." (PMID 31936151, 2020). "Deletion of negative ERK regulators, including DUSP4, DUSP6, and PEA15, induced cell death in BRAF and NRAS mutant melanomas due to unrestrained activation of ERK." (PMID 37803324, 2023). "Furthermore, we observed a negative correlation of DUSP6 and SPRY4, two negative feedback regulators of MAPK signaling with the presence of CD8+ T-cells in pre-, but not in on-treatment BRAF-mutant melanoma patients (left)." (PMID 34535668, 2021).